FOXO1 (forkhead box O1)
Diseases named in the same sentence as FOXO1 in open-access papers (continued):
Sharing a sentence is not in itself a finding about the gene and the disease.
cardiac hypertrophy (36 papers, 2010 to 2025). "A report in 2020 revealed that FOXO1 knockdown or deletion reduces cardiac hypertrophy caused by pressure overload." (PMID 34820440, 2021). "Further understanding of the crosstalk between Myh14, β-catenin, and Foxo1, will likely reveal important mechanisms regarding how Myh14 deficiency leads to cardiac hypertrophy under ISO stress." (PMID 27385019, 2016). "Of interest, in studies of calcineurin function in the pathogenesis of cardiac hypertrophy, calcineurin activity has been shown to be reduced by MAFbx, FOXO1 or FOXO3A, and to be directly linked to myocardiocyte size." (PMID 20969782, 2010). "Thus, FOXO1 may be related to the pathway of cardiac fibrosis and cardiac hypertrophy in Maine Coon cats with sarcomeric protein mutations." (PMID 34820440, 2021). "Exercise induces an increase in FOXO1 phosphorylation, enhancing its activity and potentially triggering cardiac hypertrophy, a process demonstrated to exert protective effects on the heart." (PMID 40805113, 2025). "Recent studies showed that the cardioprotective effects of AMPK activation against cardiac hypertrophy are mediated by the FoxO1/MuRF1 pathway." (PMID 35351872, 2022). "Similar to the findings in chronic intermittent hypoxia, FOXO1 induces upregulated expression of an apoptosis-related gene (Bim) and caspase 9, leading to cardiac hypertrophy in obstructive sleep apnea syndrome." (PMID 34820440, 2021). "Here, the authors unveil a previously unrecognized role of a FoxO1–Dio2 signaling axis in maladaptive, afterload-induced cardiac hypertrophy and intracellular thyroid hormone homeostasis." (PMID 32439985, 2020). "In conclusion, metformin prevented cardiac hypertrophy, and ultimately abolished myocardial apoptosis through FoxO1 pathway." (PMID 30873028, 2019). "Sirt3 was shown to promote autophagy in AngII-induced myocardial hypertrophy through the deacetylation of FoxO1 in mice." (PMID 29535606, 2018). "Dysregulation in the activity of FoxO1 has been implicated in the pathophysiology of diabetic cardiomyopathy (DCM), along with ischemic and cardiac hypertrophy, which suggests that FoxO1 is a therapeutic target for these myocardial diseases." (PMID 30083183, 2018). "Further interpretation of the interaction between Sirt3 and FoxO1 will deepen the comprehension of autophagy regulation and provide support for targeting autophagy as a new therapy for myocardial hypertrophy." (PMID 27880725, 2016). "Its activation alleviated myocardial hypertrophy by deacetylating FoxO1 and inducing its nuclear translocation, which in turn promoted cellular autophagy." (PMID 27880725, 2016). "Altogether, these results revealed that Sirt3 activation is essential to improve autophagy flux by reducing the acetylation modification on FoxO1, which in turn alleviates myocardial hypertrophy." (PMID 27880725, 2016). "Dysregulated activity of FOXO1 has been implicated in the pathophysiology of DCM, ischemic heart disease and cardiac hypertrophy." (PMID 26956801, 2016). "And FoxO1 and/or FoxO3 are/is considered as apoptosis-regulating gene for the onset of diabetic cardiomyopathy, cardiac hypertrophy and ischemic heart disease." (PMID 24489705, 2014). "Regression of cardiac hypertrophy was observed after DeTAC, accompanied by upregulation of autophagy in conjunction with upregulation of FOXO1." (PMID 25132912, 2014). "It has been reported that the upregulation of FoxO1 and FoxO3 appears to disrupt cardiac hypertrophy." (PMID 24489705, 2014). "This regression of cardiac hypertrophy was significantly attenuated by inhibition of either autophagy or FOXO1." (PMID 25132912, 2014). "The goals of this study were to 1) elucidate the role of autophagy during regression of cardiac hypertrophy, and 2) understand the role of FoxO1 in mediating regression of cardiac hypertrophy." (PMID 23308102, 2013).
cardiac hypertrophy (continued). "Taken all together, this suggests that endogenous FoxO1 is required for mediating regression of cardiac hypertrophy, possibly through stimulation of autophagy." (PMID 23308102, 2013). "FoxO1 was significantly upregulated during regression of cardiac hypertrophy, while it was downregulated during cardiac hypertrophy." (PMID 23308102, 2013). "We here demonstrate that protein expression of FoxO1 is upregulated in response to DeTAC or de-stretch and that endogenous FoxO1 is required for regression of cardiac hypertrophy." (PMID 23308102, 2013). "We here report that autophagy plays an important role in mediating regression of cardiac hypertrophy in response to mechanical unloading and that FoxO1 plays an important role in mediating autophagy and regression of cardiac hypertrophy." (PMID 23308102, 2013). "This implies that the PI3K/Akt/FoxO1 pathway might be responsible for cardiac hypertrophy due to exposure to particulate matter, thereby increasing cardiovascular risk." (PMID 40427486, 2025). "Importantly, deletion of Foxo1 in the heart, prevented cardiac hypertrophy and steatosis, in HFD-fed mice, and additionally, Foxo1 KO blunted TAC (transverse aortic constriction)-induced cardiac hypertrophic growth." (PMID 37051468, 2023). "Ginkgolide B enhances autophagy via the SIRT1/FOXO1 signaling pathway, inhibits Ang II-induced myocardial hypertrophy, and may potentially serve as a therapeutic modality for pathological cardiac hypertrophy." (PMID 37754811, 2023). "To assess whether TAC-induced increases in FoxO1 activity are required to promote maladaptive cardiac hypertrophy, we evaluated cardiac function in conscious mice by transthoracic echocardiography." (PMID 32439985, 2020). "Collectively, these data further support our hypothesis that the FoxO1–Dio2 axis plays an essential role in cardiomyocyte TH homeostasis and stress-induced pathological cardiac hypertrophy." (PMID 32439985, 2020). "Deacetylation of FoxO1 by Sirt3 promotes autophagy and alleviates myocardial hypertrophy." (PMID 27880725, 2016). "Activation of FOXO1 is an important mediator of cardiac hypertrophy." (PMID 26582913, 2016). "FOXO1 also mediates regression of cardiac hypertrophy by affecting autophagy." (PMID 24864265, 2014). "To determine whether FoxO1 is required to mediate regression of cardiac hypertrophy, we used an adenovirus harboring sh-FoxO1 (Ad-sh-FoxO1), which has been described previously." (PMID 23308102, 2013). "Taken all together, these results indicate that FoxO1 and autophagy may contribute to regression of cardiac hypertrophy in vitro." (PMID 23308102, 2013). "Therefore, HBT may regulate cardiac hypertrophy by mediating FoxO1‐dependent oxidative stress signaling." (PMID 34761560, 2022). "The dephosphorylation-mediated activation of the transcription factor forkhead box O1 (FOxO1), which plays an important role in uremic muscle atrophy, induces muscle atrophy as well as the transcriptional up-regulation of E3 ubiquitin ligase, cardiac hypertrophy, and fibrosis." (PMID 36105281, 2022). "Previous study shown that FoxO1 is required for embryonic vascular development and FoxO1-null embryo died in the early stage as a consequence of incomplete vascular growth, while the deletion of FoxO3a may results in cardiac hypertrophy and eventual cardiac failure for the offspring." (PMID 36035917, 2022). "In addition, both FoxO1 and FoxO3 negatively regulate cardiac hypertrophy." (PMID 23308102, 2013). "Thus, we hypothesized that FoxO1 may be involved in mediating the reduction in cardiac mass and cell size during regression of cardiac hypertrophy." (PMID 23308102, 2013). "Similar to FOXO1, FOXO3 has been postulated to play both a positive and negative role in autophagy related cardiomyopathy such as ischemic and cardiac hypertrophy." (PMID 24864265, 2014).
cardiac hypertrophy (continued). "However, downregulation of FoxO1 significantly attenuated DeTAC- and de-stretch-induced regression of cardiac hypertrophy, suggesting that FoxO1 may have non-overlapping functions compared to FoxO3 that induce regression of cardiac hypertrophy." (PMID 23308102, 2013). "Activation of FoxO1 and FoxO3a plays a main role in cardiac hypertrophy but unlike FoxO1, FoxO3 levels are notably reduced in uremic hearts." (PMID 36982497, 2023). "Besides, Arsenic-induced cardiac hypertrophy is mediated by reducing the expression of AMPK and FoxO1, thereby increasing the expression of NFATc3." (PMID 34305607, 2021). "Mice lacking FoxO1 are embryonically lethal by E10.5 due to impaired vasculogenesis, and mice lacking FoxO3 are viable but develop cardiac hypertrophy as adults, indicating the different functions of FoxO1 and FoxO3 in the cardiovascular system." (PMID 31264342, 2019). "Gene expression markers of cardiac hypertrophy, including Anp, Foxo1, and β-Mhc, but not Bnp and Ddk4, were also increased in the heart of Hyp mice." (PMID 30120363, 2018). "Furthermore, both FOXO1 and FOXO3 transcription factors prevent cardiac hypertrophy by stimulating the expression of atrogin-I (an E3 ubiquitin ligase) that facilitates the inhibition of calcineurin/nuclear factor of activated T cells." (PMID 26956801, 2016). "The absence of FoxO1 significantly decreased the extent of regression of cardiac hypertrophy in vitro." (PMID 23308102, 2013).
glioblastoma (36 papers, 2007 to 2025). The most malignant astrocytic tumor (WHO grade IV). "When specific to glioblastoma, both high cytoplasmic FOXO1 and pFOXO1 expression were associated with shorter OS and PFS (OS: 10 months versus 15 months for both, PFS: 8 months versus 15 months for FOXO1 and 7 months versus 12 months for pFOXO1 respectively)." (PMID 23874926, 2013). "In this study, we investigated the effects of XHP on human U-87 MG glioblastoma cell growth and its underlying mechanisms related to ROS-mediated Akt/mTOR/FOXO1 pathway, so as to provide some experimental data to the further research and development on antiglioblastoma application of XHP." (PMID 30046342, 2018). "This enzyme is crucial for glioblastoma proliferation and is linked to the overexpression of glutamate–cystine ligase (GCLC) by way of increasing the expression of the Forkhead box protein O1 (FOXO1) transcription factor." (PMID 39595047, 2024). "Conversely, our data demonstrate that CD4+ and CD8+ T cells from glioblastoma patients displayed significantly lower percentages of FOXO1 and BLIMP1 positivity compared to healthy controls." (PMID 39513882, 2024). "Perhaps targeting FOXO1, a transcriptional driver of stemness in glioblastoma, will prove more effective in the clinic than other therapies as the cancer stem cells are strongly associated with poor prognosis." (PMID 38672566, 2024). "While FOXO1 was downregulated in U87 human glioblastoma cells, which led to an increase in the number of colonies on soft agar." (PMID 37880374, 2023). "In glioblastoma, mTOR complex 2 (mTORC2) up-regulates the level of c-Myc and activates c-Myc by increasing the acetylation levels of FoxO1 and FoxO3 and then promotes glycolytic metabolism." (PMID 35689245, 2022). "In summary, this study shows an upregulation of the miR-183/96/182 cluster in EGFR-amplified glioblastoma, accompanied by reduced expression of FOXO1." (PMID 35486213, 2022). "Single-cell RNA-seq and computational analyses showed that YAP/TAZ act as master regulators of the glioblastoma stem-like cells (GSCs) by controlling a regulatory network orchestrated by FOXO1." (PMID 34439395, 2021). "The present study provided a consideration that XHP regulated glioblastoma cell apoptosis through suppressing Akt/mTOR/FOXO1 signaling cascade." (PMID 30046342, 2018). "FOXO1 is at a convergence point of receptor tyrosine kinase (RTK) signaling, which is one of the three core pathways implicated in glioblastoma." (PMID 23874926, 2013). "FOXO1 drives stem gene expression in embryonic stem cells and glioblastoma." (PMID 38672566, 2024). "As TIM-3 expression has been linked to BAT3, FOXO1, IRF4, and BLIMP1 activity and expression, we next explored whether the expressions of these corresponding genes correlate with one another in the glioblastoma micro-environment." (PMID 39513882, 2024). "In addition, endosomal mTORC2 is required for Akt-dependent FOXO1/3a and GSK3β phosphorylation in Glioblastoma cells." (PMID 38135881, 2023). "FOXO1 was also recently identified as a downstream TAZ target in glioblastoma stem cells." (PMID 34439395, 2021). "In conclusion, we demonstrate for the first time that XHP may regulate glioblastoma U-87 MG cell apoptosis via ROS-mediated Akt/mTOR/FOXO1 pathway." (PMID 30046342, 2018). "On the other hand, FOXO1 is known to prevent cell proliferation in glioblastoma." (PMID 28957313, 2017). "In glioblastoma (GBM), miR-486-5p augments the self-renewal capacity of GBM stem cells by targeting PTEN and FOXO1, thereby inhibiting the tumor suppressor network regulated by Sox2." (PMID 40710326, 2025). "Interestingly, miRNA-486-5p acts as an oncogenic miRNA by targeting the tumor suppressors PTEN and FOXO1 in human glioblastoma multiforme (GBM) spheroids." (PMID 39239557, 2024).
glioblastoma (continued). "Despite the abundance of knowledge regarding TIM-3-regulated T cell immunity, very little is known regarding the potential interplay and regulation of TIM-3 by BAT3, FOXO1, BLIMP1, and IRF4 in the glioblastoma setting." (PMID 39513882, 2024). "Inhibition of FOXO1 with AS1842856 robustly induced apoptosis in LN229, A172, LN18, U118MG, and DBTRG glioblastoma cell lines, highlighting a novel targeted therapy that disrupts circuitry required for cancer progression." (PMID 38672566, 2024). "QA acts as a metabolic checkpoint in glioblastoma by inducing NMDA receptor activation and Foxo1/PPARγ signaling in macrophages, resulting in a tumor supportive phenotype." (PMID 36927729, 2023). "This work demonstrates for the first time that FOXO1 promotes the expression of WNT pathway target genes LEF1 and TCF7 in basal‐like breast and glioblastoma multiforme cells." (PMID 37584250, 2023). "IGFBP1 is also involved in the activation of O-GlcNAcylation of FoxO1 in pancreatic β cells by promoting AKT inhibition in cancer cell response to DNA damage and it promotes angiogenesis in glioblastoma." (PMID 32526853, 2020). "FOXO1 and AKT1, along with MDM2 (another common intermediary gene in the PIN) have previously been identified in differential co-expression studies of glioblastoma." (PMID 28957313, 2017). "To further validate these findings, we investigated whether changes in the percentage positivity levels of BAT3, FOXO1, BLIMP1, and IRF4 intracellular proteins are observed in T and NK cells from glioblastoma patients compared to healthy controls." (PMID 39513882, 2024). "Indeed, forced expression of miR-486-5p enhanced the self-renewal capacity of glioblastoma neurospheres, while inhibition of endogenous miR-486-5p activated PTEN and FoxO1 and induced cell death." (PMID 39766136, 2024). "Similarly, the percentages of FOXO1 and BLIMP1 were also reduced in glioblastoma versus healthy donor CD4+ and CD8+ T cells and NK cells." (PMID 39513882, 2024). "Compared with control, CTNND1 expression was up-regulated in glioblastoma tissues whereas FOXO1 indicated no differential expression." (PMID 31889897, 2019).
endometrial cancer (35 papers, 2010 to 2025). Primary or metastatic malignant neoplasm involving the endometrium (mucous membrane that lines the endometrial cavity). "Up-regulated miR-182 in endometrial cancer is reported to be associated with the repressing FOXO1 gene, which is known to be down-regulated in endometrial cancer compared to normal endometrial." (PMID 24363810, 2013). "Forkhead box protein O1 (FOXO1) inhibits endometrial cancer growth by suppressing angiogenesis and promoting apoptosis." (PMID 38893244, 2024). "The abnormal expression or activity disturbance of the FOXO1 transcription factor is related to multiple gynecological diseases, such as endometrial cancer, endometriosis, and ovarian dysfunction, which in turn highlights its potential as a therapeutic target." (PMID 37762313, 2023). "Mir-205 has also been shown to promote tumor proliferation by targeting estrogen-related receptor-γ in endometrial carcinoma and contributes to paclitaxel resistance and progression of endometrial carcinoma by downregulating FOXO1, a tumor suppressor." (PMID 37958433, 2023). "The recent study shows that FOXO1 induces irreversible G1 arrest and cellular senescence through the PR-B/FOXO1/p21 Cip1 axis in endometrial cancer." (PMID 35723050, 2022). "FOXO1 is a putative tumor suppressor, and its gene expression is dysregulated in some cancers, including endometrial cancer and melanoma." (PMID 33849069, 2021). "In endometrial cancer, miR-9, miR-27a, miR-96, miR-128, miR-153, miR-183 and miR-186 also function cooperatively to suppress FOXO1-regulated cell cycle arrest and cell death." (PMID 32372224, 2020). "Conversely, knockdown of FOXO1 expression using siRNA partially attenuates the antiproliferative effect of metformin on endometrial cancer cells." (PMID 30211120, 2018). "Our study shows a marked loss of AMP‐activated protein kinase (AMPK) phosphorylation and nuclear human Forkhead box O1 (FOXO1) protein in estrogen‐dependent endometrial cancer (EC) tumors compared to normal control endometrium." (PMID 27636742, 2016). "It would be interesting to determine the significance of the PR and FOXO1 cooperation in the other progesterone-responsive genes that were influenced by AKT inhibition in endometrial cancer." (PMID 22911820, 2012). "We have demonstrated a cooperation of PR and FOXO1 in regulating genes in endometrial stromal cells and thus it is likely that PDK4 upregulation by progestins requires both PR and FOXO1 in endometrial cancer cells." (PMID 22911820, 2012). "Since genistein-induced expression of PR and FOXO1 induces endometrial decidualization, it may be useful for maintenance treatment in young patients with endometrial cancer who wish to preserve their fertility." (PMID 35717540, 2022). "Additionally, LINC00261 is able to bind to hsa‐miR‐182, hsa‐miR‐183, hsa‐miR‐153 and hsa‐miR‐27a; further, hsa‐miR‐96 was able to regulate FOXO1 mRNA expression, suppressing cell proliferation, migration and invasion of endometrial cancer cells." (PMID 32860342, 2020). "Another recently-reported target of metformin in endometrial cancer is the transcription factor forkhead box protein 1 (FOXO1), which plays numerous roles in cellular function, including regulation of gluconeogenesis, adipogenesis, protection from oxidative stress, and tumor suppression." (PMID 30211120, 2018). "Downregulation of FOX transcription factors is a common theme of this cluster, as miR-183/96/182 have been demonstrated to inhibit FOXO1 in classical Hodgkin lymphoma and in endometrial cancer as well, resulting in decreased G1 cell cycle arrest and cell death." (PMID 24627810, 2014). "Interestingly, the same endometrial cancer study mentioned previously for miR-9 also found that miR-153 has similar oncogenic properties, appearing to down-regulate FOXO1 and apoptosis." (PMID 23335942, 2012).